NPY (neuropeptide Y)
Diseases named in the same sentence as NPY in open-access papers (continued):
Sharing a sentence is not in itself a finding about the gene and the disease.
tumor (continued). "Similarly, NPY promotes or counteracts tumor development; therefore, the peptide favors tumor cell growth, migration, metastasis, and angiogenesis in some tumors, whereas, in others, it exhibits an antitumor effect." (PMID 37373115, 2023). "This high NPY levels may result from both the endogenous peptide expression in tumour cells and its presence in neuronal structures." (PMID 36583743, 2023). "The L-Lys modified by ortho-carboane was conjugated with [F7, P34]-NPY to obtain [K4-Nε(Cpa)]-[F7, P34]-NPY, which makes this molecule have extremely high affinity even at the nanomolar level and easy to be selectively ingested by tumor cells of the corresponding subtype." (PMID 35433432, 2022). "There was also a slight positive correlation between NPY expression and tumor cell proliferation." (PMID 35418942, 2022). "NPY is an important regulator of tumor progression of nerve or endocrine related cancers." (PMID 35433681, 2022). "In addition, resistance to the hormones Neuropeptide Y (NPY) and Agouti-related protein (AgRP), which promote food intake, has also been observed in tumor-bearing animals." (PMID 35455957, 2022). "Angiogenic factors are released mainly by tumor and endothelial cells; however, some sympathetic nerve fibers may release NPY, which is a potent angiogenic factor." (PMID 36139532, 2022). "Activation of Y1R and Y2R by NPY leads to tumor cell proliferation, angiogenesis and metastasis." (PMID 35433681, 2022). "Taken together, the neuropeptides CGRP and NPY were suggested to impair the anti-tumor immunity and their inhibition may be a potential strategy for cancer treatment." (PMID 34395421, 2021). "The NPY transcripts in CRCs are lower than in non-tumor tissues." (PMID 34627187, 2021). "In prostate cancer, depression-induced NPY secretion might promote the tumor infiltration of myeloid cells and therefore contribute to cancer progression." (PMID 34395421, 2021). "Y2 receptor agonists specifically stimulated GTPγS binding, and nanomicelles targeting the Y1 receptor prolonged the survival rate in GBM murine models, indicating that NPY-activated Y1 and Y2 receptors might participate in tumor growth." (PMID 34068501, 2021). "Paradoxically, NPY appears to reduce the invasive potential of tumor cells in vitro." (PMID 34627187, 2021). "However, a tendency towards lower ND was noted in the peripheral tumor area of PCa in tumors with a high NPY expression (p=0.07)." (PMID 34277455, 2021). "We analyzed the correlation between NPY and the parameters of tumor innervation." (PMID 34277455, 2021). "In addition to its numerous physiological functions, NPY exhibits pleotropic effects relevant to tumor biology, such as stimulation of angiogenesis, cell proliferation, migration, chemoresistance, and regulation of stem cell differentiation." (PMID 33681186, 2020). "Consequently, the expression of both NPY and Y5R is elevated in chemoresistant NBs and cell lines developed from recurrent tumors, while Y5R antagonist inhibits NB tumor growth via pro-apoptotic effects." (PMID 33681186, 2020). "Notably, MTX was specifically delivered to tumor cells by exploiting the hY1R-preferring peptide [F7,P34]-NPY." (PMID 32733853, 2020). "Moreover, Y2R expressed in endothelial cells mediates the angiogenic effect of NPY and thereby contributes to tumor vascularization." (PMID 33681186, 2020). "Immunohistochemistry identified elevated NPY levels in CCA tumor samples from 48 patients." (PMID 32069926, 2020). "High baseline levels correlate with short survival, and monitoring plasma tumor DNA using NPY methylation during treatment may predict early effect and later progression." (PMID 31731482, 2019). "Neuropeptide Y is highly relevant to tumor cell proliferation and survival." (PMID 31480483, 2019). "Early reports have pointed towards NPY methylation as a marker of tumor specificity." (PMID 31731482, 2019).
tumor (continued). "We hypothesized that tumor specific methylation of NPY in plasma DNA correlated with ctDNA measured with DNA nucleotide mutation." (PMID 31731482, 2019). "The down-regulation of NPY expression inhibited local bone destruction in primary tumors, as manifested by the presence of extended segments of intact bone surface adjacent to the tumor tissue." (PMID 25714031, 2015). "Moreover, the most intense NPY immunostaining among all cell fractions tested was seen in groups of CD99-positive tumor cells invading the bone." (PMID 25714031, 2015). "Therefore, in the subset of such VEGF-insufficient tumors, hypoxia-induced activation of the NPY system is essential to maintain tumor vascularization by direct stimulation of ECs and up-regulation of VEGF system." (PMID 24318733, 2013). "Moreover, receptors of regulatory peptides such as NPY are in the focus of approaches to tumor targeting and molecular imaging of cancer." (PMID 23236424, 2012). "As the effect of NPY on tumor cell growth is controversially discussed in the literature, the influence of NPY on the growth of MCF-7 cells with particularly high Y1 receptor status (tamoxifen low sensitive subclone (L)) was investigated in the kinetic chemosensitivity assay." (PMID 23236424, 2012). "The high expression and functionality of the Y1R supports speculations on a role of NPY in tumor growth, as suggested, for instance, for SK-N-MC and MCF-7 cells." (PMID 23236424, 2012). "In consequence, NPY can either stimulate or inhibit tumor growth, depending on tumor type." (PMID 20508839, 2010). "However, proangiogenic actions of NPY can be altered by its direct effect on tumor cell proliferation and survival." (PMID 20508839, 2010). "Thus, these direct effects on tumor cell proliferation and survival are an important aspect of NPY actions in tumors and are often potent enough to overcome its angiogenesis-mediated growth-promoting effect." (PMID 20508839, 2010). "Consequently, treatment with exogenous NPY significantly increased vascularization of subcutaneous xenografts derived from both tumor cell types." (PMID 20508839, 2010). "ProNPY/NPY processing generated molecular forms of NPY with known differences in NPY-receptor selectivity, implicating a potential for in vivo modulation of NPY-like effects in tumour tissue." (PMID 10901366, 2000). "These alterations collectively facilitate tumor proliferation and progression.2)Sympathetic Activation: Activation of the sympathetic nervous system releases norepinephrine (NE), which binds to β2-adrenergic receptors (β2AR) on tumor cells and induces secretion of neuropeptide Y (NPY)." (PMID 41000397, 2025). "A prodrug (doxorubicin-P18) based on neuropeptide Y analog showing cancer microenvironment responsiveness has been developed to fight triple-negative BC cells: this prodrug exerted a higher suppression of tumor growth and metastasis than the administration of free doxorubicin." (PMID 41301028, 2025). "This suggests that NPY could also play a role in tumor development in human patients with PC." (PMID 40073121, 2025). "The development of multifunctional NPY-conjugates for selective nuclear delivery of radio lanthanides (targeted radionuclide therapy) is a promising strategy to deliver therapeutically active cargos (e.g., radiometals) into tumor cells overexpressing peptide receptors (e.g., Y1R)." (PMID 37373115, 2023). "Moreover, NPY3-36 also favored the migration of tumor cells and angiogenesis, and intratumoral endothelial cells showed Y2R, expressed under hypoxia conditions, and mediated the proliferative action promoted by NPY." (PMID 37373115, 2023). "Hence, such an accumulation of NPY receptor-positive tumour cells in areas of PNI suggests that NPY secreted from the neuronal cells may act as a chemoattractant for PCa." (PMID 36583743, 2023).
tumor (continued). "Comparative analysis of our data with TCGA and CPTAC cohorts showed that both NPY and FAIM2 hyper-methylation and down-regulations can be novel epigenetically regulated genes in the Indian patient population, statistically significantly associated with poor survival and advanced tumour stages." (PMID 36329447, 2022). "Interestingly, hypoxia could induce upregulation of Y2R/Y5R expression to trigger the NPY/Y2R/Y5R axis, which stimulated tumor cell proliferation, survival, migration and angiogenesis in EWS." (PMID 35719404, 2022). "Notably, the effect of the NPY or NPY receptors on tumor cell growth is controversially discussed." (PMID 35087836, 2021). "In our risk model, the expression of five genes (PODN, NPY, MICU3, TUBB6 and RHOJ) was decreased in tumor tissues, and the greater the degree of downregulation was, the better the prognosis was, indicating that the hypermethylation of these genes may play a protective role in GC patients." (PMID 32174791, 2020). "A stimulating (e.g., epinephrine, NE), inhibiting (e.g., dopamine, SM), as well as dual role (stimulating or inhibiting) (e.g., NPY) of Nts and NPs on tumor angiogenesis has been described, which might suggest the role of these molecules in progression and metastasis of tumors (including CRC)." (PMID 32429087, 2020). "Thus, while the translocation type may be responsible for differential expression of anti-osteogenic and osteolytic factors, including NPY, their levels can be further modified in the tumor microenvironment, as suggested by our current and previous data." (PMID 25714031, 2015). "Therefore, disrupting proper osteoblast differentiation and bone formation by tumor-derived NPY may facilitate bone degradation via shifting the balance toward osteolysis." (PMID 25714031, 2015). "The elevated ETV5 then transcriptionally represses the tumor suppressor neuropeptide Y (NPY), facilitating EPN tumor formation." (PMID 40599851, 2025). "Both populations expressed classical adrenergic markers NPY and DBH in the core of the tumor, and this core was surrounded by macrophages, cancer-associated fibroblasts, and Schwann cell-lineage components in the periphery." (PMID 41279557, 2025). "In primary tumors, neuroblast clusters expressing adrenergic markers (e.g., NPY and DBH) dominated the tumor core and were bordered by stromal and immune components, with limited T cell infiltration." (PMID 41279557, 2025). "Mechanistically, NPY activated ERK and Smad2 via NPY1R, synergising with TGFβ signalling in tumour cells expressing TβRI." (PMID 41298817, 2025). "Here, the authors report that low-BMI increases neuronal secretion of neuropeptide Y (NPY), thereby activating the NPY receptor on lung tumor cells, leading to tumor metabolic reprogramming and brain metastasis." (PMID 40595538, 2025). "Hence, it is crucial to know the YR types that express tumor cells, the G proteins involved in these mechanisms, and the signaling pathways activated by the different YRs in order to explain cancer/anticancer actions mediated by NPY and PYY and to develop specific antitumor strategies." (PMID 37373115, 2023). "We have developed a tumor microenvironment responsive transformable prodrug DOX‐P18, in which a novel NPY analogue was connected to chemotherapeutic DOX using MMPs‐cleavable peptide PLGVRG as a bridge." (PMID 37147783, 2023). "NPY-loaded immune stimulating complexes (ISCN formulation) decreased growth and cytokine levels in MCF-7 tumor cells; cells were blocked in the G0/G1 phase, and many suffered apoptosis after treatment with the ISCN formulation." (PMID 37373115, 2023). "We found that these genes are primarily related to different pathological process resulting in the suppression of tumor progression, such as GNG4 and NPY." (PMID 37058060, 2023). "In such an interface, NPY can be cleaved by FAP (fibroblast activation protein), a dipeptidyl peptidase upregulated in tumor-activated mesenchymal cells in the stroma." (PMID 37373115, 2023).
tumor (continued). "Perivascular denervation of sensory fibers (NPY, VIP, SP) and adrenergic fibers of blood vessels present in the stroma and the submucosa adjacent to the tumor have been observed in colon cancer studies." (PMID 36139532, 2022). "Further, tumor-derived platelets biomarkers, as KLK3, FOLH1, and NPY, enable prediction after abiraterone therapy in castration resistant prostate cancer (CRPC) and KLK2, KLK3, and FOLH1 were associated with short OS." (PMID 33673461, 2021). "Using Crystal Digital PCRTM, the NPY and WIF1 hypermethylation testing was performed on the 23 tumor tissues from CRC patients." (PMID 34627187, 2021). "A significant hypermethylation of NPY and WIF1 in the tumor tissues was demonstrated (p < 0.001 for NPY; p < 0.001 for WIF1)." (PMID 34627187, 2021). "A fluorine-18 (18F)-labeled, fluoroglycosylated [F7,P34]-NPY analog was synthesized and enabled the visualization of hY1R-expressing MCF-7 tumor cells in a xenograft mice model." (PMID 32733853, 2020). "The current findings provide novel direct epigenetic evidence for the involvement of SST, TAC1, hypocretin neuropeptide precursor (HCRT), neuropeptide Y (NPY), and GAL in the process of tumor suppression in humans." (PMID 29682090, 2018). "While strong NPY immunostaining was observed across the entire SK-ES1 xenograft tissue, its intensity was significantly higher in tumor tissue adjacent to the bone, as compared to regions distant from the bone invasion area." (PMID 25714031, 2015). "Similar up-regulation of the NPY system was reported in ischemic tissues, while DPPIV was elevated in various hypoxic tumor cells." (PMID 24318733, 2013). "We used two multiplex assays, namely Alb-Fam/WIF1-Vic and the NPY-Ned/PENK-Vic, to measure methylation of our three biomarkers in a set of 15 paired normal and tumor tissue samples." (PMID 24289328, 2013). "Our results show that the expression levels of NPY, HASH-1and dHAND were found decreased in intermittent hypoxia conditioned tumor cells." (PMID 22363512, 2012). "We focused in those genes that were significantly differently methylated in the basal-like tumor subtype (HOXA9, SOX1, VAMP8, and TNFRS10D) and those that were significantly hypermethylated in the luminal B tumors (NPY, RASSF1, HS3ST2, DBC1, FGF2, CD40." (PMID 20920229, 2010). "We show that tumor-induced factors involved in inflammation (unpaired 3/ Interleukin-6-like) and reduced insulin signaling (ImpL2/ Insulin Growth Factor Binding Protein) decrease NPF (Neuropeptide F/ Neuropeptide Y) in the brain prior to organ wasting." (PMID 41792134, 2026). "Here, we identify that NPY and its receptor, Npy1r, are up-regulated in the highly metastatic genetically engineered KPR172HC mouse model of PC and demonstrate that both ligand and receptor are expressed in the primary tumor as well as liver metastases." (PMID 40073121, 2025). "Consequently, the expression of all elements of the NPY system was higher in EPE areas, as compared to the corresponding main tumour mass (NPY and Y1R, p = 0.008; Y2R = 0.016; Y5R, p = 0.031)." (PMID 36583743, 2023). "In the tumour microenvironment, NPY represents a common mediator of various neuronal and non-neuronal effects, since it is synthesized by tumoural cells and nerves." (PMID 36583743, 2023). "Proteomic profiling study of primary PCa revealed that high pro-NPY expression, regardless of the ERG status, was associated with an increased PCa-specific risk of death, especially in patients with Gleason score ≤ 7 tumours." (PMID 36583743, 2023). "The same absence is observed with the tumor stage (p = 0.2873 for NPY; p = 0.0517 for WIF1; non-parametric Kruskal-Wallis test, n = 22)." (PMID 34627187, 2021). "In our study, no signicant differences were observed between female and male patients concerning methylation of NPY (p = 0.055 for non-tumor tissues and p = 0.13 for tumor tissues)." (PMID 34627187, 2021). "NPY increases MDSCs in the tumor site, and, induces IL6 release by tumor cells and MDSCs." (PMID 32516941, 2020).
tumor (continued). "The modified conjugates [K4(GFLG-MTX),F7,P34]-NPY displayed high extracellular stability, paired with a fast uptake into cancer cells and the rapid release of MTX led to high cytotoxicity values in hY1R expressing tumor cells (Böhme and Beck-Sickinger, 2015)." (PMID 32733853, 2020). "The available transgenic mouse lines that are commonly used to phenotype POMC and NPY neurons (POMC-eGFP and NPY-eGFP mice, eGFP: enhanced green fluorescent protein) cannot be used as tumor recipients for our model because of an incompatible genetic background." (PMID 28475119, 2017). "Hypothalamic NPY gene expression did not change in 85As2 tumor-bearing rats as compared to that in non-tumor-bearing rats." (PMID 28249026, 2017). "Of note, no bone metastases and any distant tumor dissemination was also observed in mice injected with another ES cell line characterized by low NPY release, SK-N-MC (data not shown)." (PMID 25714031, 2015). "Importantly, differences in NPY expression observed in vitro between SK-ES1 and TC71 cell lines were preserved in vivo, within primary tumor tissues." (PMID 25714031, 2015). "However, another study showed that tumor development was neither reduced nor delayed by calorie restriction in NPY knockdown animals, which were used as an appetite suppression model." (PMID 37373115, 2023). "Thus, this project aimed at performing a comprehensive immunohistochemical analysis of the NPY system tissue expression in primary PCa tumours, bone metastases, PIN and non-neoplastic prostate." (PMID 36583743, 2023). "Y2R inhibitors, not Y1R/Y5R inhibitors, inhibited the tumor growth blockade mediated by NPY." (PMID 37373115, 2023). "Interestingly, statistical analysis did not reveal any correlations between NPY and clinicopathological features, such as age, tumour grade and proliferation index." (PMID 36583743, 2023). "Further assessment were also reinvestigated, patients showing lower expression had poor disease prognosis (log rank p = 0.01) than patients with higher expressions of NPY and FAIM2 in their tumours, which could be indirectly controlled by differential methylation." (PMID 36329447, 2022). "Importantly, significant hypermethylation of both genes was demonstrated in tumor tissues compared to adjacent non-tumor tissues (NPY p = 0.001; WIF1 p = 0.002; non-parametric Wilcoxon paired-series test)." (PMID 34627187, 2021). "There are no studies directly linking NPY with stress-induced tumor growth and progression." (PMID 20508839, 2010). "Two sources of NPY may be distinguished in cancer cells: paracrine from the nerves within the microenvironment, and autocrine synthesis which allows for neuronal and non-neuronal modulation within tumor components." (PMID 34277455, 2021). "However, in the same mice, sympathectomy also induces upregulation of NPY in tumor tissue making it unclear as to whether the absence of sympathetic NPY, the induction of tumor NPY, or another sympathetic neurotransmitter contributes to the anti-tumorigenic effect." (PMID 35418942, 2022). "The NPY and WIF1 methylation testing was performed on the 11 pairs of tumor/non-tumor tissue adjacent to the tumor." (PMID 34627187, 2021). "The local cohort study confirmed that NPY and WIF1 were significantly hypermethylated in tumor tissues compared to adjacent non-tumor tissues (WIF1 p < 0.001; NPY p < 0.001; non-parametric Wilcoxon paired-series test)." (PMID 34627187, 2021). "Comparing tumor samples and non-tumor colonic tissues, TCGA data were analyzed for WIF1 and NPY transcripts." (PMID 34627187, 2021). "This is confirmed in tumor DNA extracted from a biopsy for which no methylation of the MLH1 gene promoter was found, whereas methylation of the NPY and WIF1 genes was observed." (PMID 34627187, 2021).